IL6 (interleukin 6)
Diseases named in the same sentence as IL6 in open-access papers (continued):
Sharing a sentence is not in itself a finding about the gene and the disease.
tumor (continued). "The just‐mentioned immunosuppressive mechanism in the tumor microenvironment is supported by an autoinflammatory loop regulated via the IL‐1β/IL‐6/signal transducer and activator of transcription 3 (STAT3) axis." (PMID 38775220, 2024). "Pro-inflammatory cytokines, such as interleukin (IL)-1β, IL-6, and IL-8, can classically activate macrophages to the M1 phenotype, mounting an anti-tumor immune response." (PMID 39256888, 2024). "In tumors, IL6 is involved in the recruitment of mesenchymal and endothelial cells, contributing to tumor progression." (PMID 38540309, 2024). "IL-1 and IL-6 are upregulated in many cancers, contributing to a pro-inflammatory state that fosters tumor growth and immune evasion." (PMID 39298504, 2024). "In all patients with an IL-6 level below 5.0 pg/mL in C2, tumour regression TRG1a/1b according to the Becker classification and ypN0 were detected in postoperative histopathological specimens." (PMID 38398148, 2024). "In responsive patients, tumor tissues gradually regress, and the highly activated state of the immune system diminishes, resulting in a gradual decline in IL-6 and IL-8 serum levels." (PMID 38774604, 2024). "As an example, it has been shown that tumor-exposed LECs significantly increase their IL-6 production, and thereby promote tumor cell invasion and proliferation." (PMID 37971882, 2024). "In the tumor microenvironment, IL6 serves as a major cell factor and participates in the development of several cancers." (PMID 38831470, 2024). "On the contrary, tumor β-catenin signaling disrupts cDC1 recruitment in melanoma, and tumor production of factors such as IL-10, IL-6, TGF-β, and PGE2 suppresses DC function and maturation." (PMID 38903502, 2024). "First, pro-inflammatory cytokines such as TNF-α, IL1, and IL6 promote tumor cell death and inhibit tumor growth." (PMID 38534922, 2024). "Targeting the TGF-β1/IL-6 pathway has been shown to reduce tumor burden and metastasis in vivo while enhancing neuroblastoma cell sensitivity to chemotherapy, underscoring the therapeutic potential of interrupting this pathway." (PMID 39286635, 2024). "CRP and IL-6, known markers of systemic inflammation, demonstrated significant increases with disease progression, consistent with their role in the tumor microenvironment." (PMID 39816276, 2024). "Focusing on the tumor-specific role of IL-17 in cancer, it also signals TAMs to generate an additive effect on IL-6 function." (PMID 38279220, 2024). "NO can upregulate Notch signaling and IL-6 signaling in tumor cells, leading to prolonged STAT3 activation and promoting cancer cell stemness." (PMID 38254796, 2024). "Inflammatory cytokines, such as interleukin (IL)-1, IL-6, IL-10, tumor necrosis factor-α, macrophage migration inhibitory factor, and transforming growth factor-β, are involved in tumor initiation and progression." (PMID 38267838, 2024). "Tumor necrosis factor and interleukin-6 released by the tumor and surrounding cells can suppress protein synthesis and stimulate protein degradation." (PMID 38913646, 2024). "In contrast, cell lines in advanced tumor stages showed slightly reduced soluble CD155 production after IL-6 stimulation." (PMID 39596207, 2024). "Of note, IL-6 can be produced by different cell types in the TME contributing to tumor development through direct and indirect pathways." (PMID 39030280, 2024). "The IL6-JAK-STAT3 signaling pathway is known to promote tumor cell resistance to chemotherapy and αEGFR-E-P125A treatment downregulates IL6-JAK-STAT3 signaling." (PMID 38315147, 2024). "IL-1β stimulates the release of prostaglandins, IL-6, and MMPs, promoting angiogenesis, tumor metastasis, and invasion." (PMID 39872848, 2024). "The uptake of tumor-derived EVs harboring oncogenic HRAS gene by neutrophils enhances IL-6 production and tissue factor activation in xenograft mice, resulting in a proinflammatory response." (PMID 38741166, 2024).
tumor (continued). "Our results demonstrated that AQP3 relied on the PPAR-γ/NF-κB axis to regulate tumor occurrence and progression by mediating M2 macrophage polarization and IL-6 secretion." (PMID 39060229, 2024). "Different mechanisms have been identified as drivers of NET formation, indirectly by the immune cells in the TME, or directly by the tumor cells by releasing various molecules such as IL-1, IL-6, IFN, TNF-α, C3a, HMGB1, or G-CSF." (PMID 39001538, 2024). "It is known that IL-6-induced STAT3 activation promotes cell survival, tumor EMT in vitro, and is associated with elevated p-STAT3 levels in GC tissues." (PMID 38805119, 2024). "Targeting epigenetic biomarkers such as miR-182-5p regulates IL6, its receptor complex, and signaling pathways, resulting in regression of tumor burden." (PMID 39766086, 2024). "The secretion of factors such as IL-6 and IL-8 by metabolically reprogrammed CAFs can activate signaling pathways in adjacent tumor cells, promoting their proliferation and survival." (PMID 39519109, 2024). "This mini-review discusses IL-6 and VEGF as two examples of tumor-derived cytokines and growth factors in causing PNS and CCA." (PMID 38482486, 2024). "IL-1β induces tumor angiogenesis through activation of the vascular endothelial growth factor pathway, increases immunosuppressive cells, and accelerates tumor invasion via secretion of GM-CSF and IL-6." (PMID 38580797, 2024). "Tumour‐associated macrophages (TAMs) in the TME can promote tumour progression and metastasis by releasing cytokines, such as IL‐6." (PMID 37974543, 2024). "Interventions that block signaling by IL-1β and IL-6 suppress tumor growth in various mouse models of PDAC." (PMID 39260693, 2024). "Lastly, the potential activation of downstream pathways in the tumor tissue, possibly due to IL-6 trans-signaling, needs to be assessed." (PMID 38672257, 2024). "IL-6, binding its receptor on tumor cells membrane, activates the IL-6-JAK-STAT axes and the NOTCH signaling pathway promoting cell proliferation and the acquisition of an invasive phenotype." (PMID 39015505, 2024). "Following pFUS, there was a 75% concordance for anti-tumor cytokines and inflammatory markers (including TNFα, IL-1a, IL-1b, IL-17, IL-6, and VCAM-1), indicating a TME shift toward a hot TME." (PMID 38543305, 2024). "IL-6 is an inflammatory cytokine produced by macrophages that promotes tumor growth and progression by promoting chronic inflammation." (PMID 38693593, 2024). "Previous studies reported that plasma levels of IL-6 were positively correlated with tumor size in patients with cardiac myxoma." (PMID 38396907, 2024). "IL-17 activates Stat3 in tumor and tumor stromal cells through an IL-6-dependent mechanism, upregulating prosurvival and proangiogenic genes." (PMID 38339010, 2024). "This induction of VEGF expression highlights IL-6’s role in promoting angiogenesis, particularly in the context of tumor growth." (PMID 39759107, 2024). "Further studies have revealed that the tumor pro-proliferative effects of NF-κB are mediated indirectly through IL-6 and related cytokines produced by myeloid cells." (PMID 39493763, 2024). "O‐glycan truncation in tumor cells promoted the M1 polarization of macrophages, enhanced T‐cell‐mediated cytotoxicity, and reduced interleukin‐6 (IL‐6) levels in the secretome." (PMID 37452653, 2024). "Studies have confirmed that chitosan-based biomaterials can promote mitochondria-induced apoptosis, promote tumor cell antioxidants, and reduce the production of IL-8, IL-6, TGF-β, and TNF-α to achieve anti-inflammatory effects." (PMID 39161903, 2024). "We stratified patients based on stage of tumor, histological grade of cancer cells, or site of tumor, respectively, to compare the serum IL-6 levels between different patients groups." (PMID 38978990, 2024).
tumor (continued). "Thereafter, we compared the differential genes of TAMs in normal tissue, early LUAD tissue, and the advanced LUAD TME, and found that IL-6 secretion was significantly different among the three groups, increasing with tumor progression." (PMID 38424624, 2024). "As deleterious functions, IL-6 participates in promoting chronic inflammatory microenvironment, thereby supporting tumor development." (PMID 38323313, 2024). "The administration of anti-IL6 antibodies during exercise blocks IL-6 signaling and reduces exercise-induced tumor growth suppression." (PMID 39595094, 2024). "The intrinsic actions of IL-6 on tumor cells have an impact on the development of cancer by affecting cell survival, proliferation, and metastatic dissemination." (PMID 38803729, 2024). "The aims of this study were to investigate the effects of ART1 knockdown on IL-6-induced cell proliferation in vitro and use an in vivo murine model to observe the growth of transplanted tumours." (PMID 38504172, 2024). "IL-6 has been identified as an important tumor-promoting cytokine that enforces proliferation and anti-apoptotic effects in tumor cells." (PMID 38561726, 2024). "Mechanistically, IL-6 exerts its effects on tumor initiation, progression, angiogenesis, immune modulation, and metastasis primarily via the STAT3 pathway." (PMID 38689325, 2024). "WMW regulated NF-kB/IL-6/STAT3 pathway to balance between tumor-promoting and tumour-suppressing bacteria, thereby attenuating CAC." (PMID 38783955, 2024). "These extracellular vesicles can subsequently inhibit T cell immunity in the tumor microenvironment by promoting macrophage secretion of interferon and IL-6." (PMID 39763653, 2024). "In patients with malignant tumors, CRP levels are modulated by cytokines, particularly interleukin-6, which is produced by tumor or surrounding cells." (PMID 39513125, 2024). "The pro-inflammatory cytokines (TNF-α, IFN-γ, and IL-6) in both mouse plasma and tumor tissues showed a significant increase after treatment with PAC-SABIs, while a notable decrease was observed in the anti-inflammatory cytokine TGF-β." (PMID 38971872, 2024). "The average increase in serum IL-6 levels among patients with ablated tumor size of ≤ 3 cm and > 3 cm were 8.62 ± 7.95 pg/ml and 15.40 ± 11.43 pg/ml, respectively." (PMID 38430269, 2024). "Tumour cell derived‐MUC1 can interact with nuclear factor‐kappa B (NF‐κB) to induce the expression of interleukin‐6 (IL‐6), an essential cytokine for fibroblast activation and migration." (PMID 38778448, 2024). "The most important sources of IL-6 are represented by macrophages, B and T lymphocytes, fibroblasts, endothelial cells, and tumor cells." (PMID 39452544, 2024). "The JAK/STAT3 signaling pathway is vital in mediating the effects of IL-6 on tumor cell proliferation, survival, invasion, and metastasis." (PMID 39136000, 2024). "IL-6 plays a crucial role in the tumor microenvironment, and it is the most abundant cytokine in this setting." (PMID 38928482, 2024). "As a result, IL-6 has been proposed as critical mediator of the connection between tumor necrosis, local and systemic inflammation, and patient outcomes in colorectal and other cancers." (PMID 38689325, 2024). "It is well known that IL-12 leads to an increased expression of pro-inflammatory cytokines, however we also investigated the role of IL-6 and IL-8 for tumor immunosuppression in GBM." (PMID 38161192, 2024). "The JAK/STAT3 signaling mediates the impact of IL-6 on tumor cell proliferation, survival, invasion, and metastasis as well as the suppression of anti-tumor immunity." (PMID 39247610, 2024). "IL11 expression was increased 40-fold in KPP tumors when compared to adjacent non-tumor epithelium, while IL6 expression remained comparable between these two compartments." (PMID 39128004, 2024).
tumor (continued). "Recently, IL-6 blockade was found to promote tumor immunity through activation of the immunostimulatory IL-12 pathway, while abrogating the toxicity of checkpoint blockade, thus decoupling tumor immunity from autoimmune toxicity." (PMID 39399167, 2024). "IL6high iCAF exhibited a distinct ligand expression involving IL6, which interacted with migratory tumor and M1/M2-like TAMs through IL6R, and HRH1 in endothelial cells to activate the inflammatory response and angiogenesis." (PMID 38892065, 2024). "Under inflammation such as inflamed tumor microenvironment with PD‐1/PD‐L1 interaction between immune cells/tumor cells, respectively, inflammatory cytokines, such as IL‐6, are released from various cells in the tumor microenvironment including fibroblasts." (PMID 39300829, 2024). "IL-6 produced by tumor cells can contribute to the differentiation of hematopoietic stem and progenitor cells (HSPC) into monocyte-dendritic progenitor cells (MDPs)." (PMID 38464516, 2024). "In N3tg DP tumor T-cells, the constitutive activation of canonical NF-κB allows a stronger binding of the p65 subunit to the IL-6 promoter, thus enhancing its transcription." (PMID 39337370, 2024). "The intrinsic ability of IL-6 induces tumor-activating pathways such as JAK/STAT, Ras/MAPK, and PI3K/AKT, which together culminate in stabilizing the anti-inflammatory subsets in the TME." (PMID 38279220, 2024). "IL-6/STAT3 signaling plays a crucial role in modulating tumor-infiltrating immune cells within the tumor microenvironment." (PMID 39830506, 2024). "ROS can induce MAPK signaling activation, regulating the secretion of NF-κB-mediated inflammatory cytokines such as IL-1β, IL-6, and tumor necrosis factor-α, thereby modulating tumor cell inflammatory responses." (PMID 39763653, 2024). "NF-κB is overexpressed in the PCa TME and regulates the expression of numerous tumor-promoting genes including cyclin-D1, IL-6, TNFα, VEGF, IL-8 and IL-1β." (PMID 39335188, 2024). "In experimental animal models, administration of monoclonal antibodies against IL-6 or an IL-6 receptor antagonist significantly inhibited the progression of cancer cachexia in tumor-bearing mice." (PMID 38510850, 2024). "IL-6-mediated STAT3 activity in tumor cells can stimulate the release of factors, such as VEGF and IL-10, that inhibit DC maturation." (PMID 38254801, 2024). "In this study, the role and mechanism of PD-L1 in tumor immune escape were explored, with particular focus on the promotion of IL-6 and IL-4 secretion by activation of the Notch-1/IRE1/XBP1s signaling pathway in macrophages." (PMID 38261741, 2024). "BRDs and BETs can inhibit or activate the assembly of the transcriptional machinery regulating the production of inflammatory cytokines with crucial functions in tumor progression (IL-1b, IL-6, TNFa, and MCP-1)." (PMID 39516356, 2024). "For example, inhibition of IL-6 signaling dramatically impedes tumorigenesis and extends the tumor-free survival of patients following surgical partial hepatectomy." (PMID 38890694, 2024). "As an indication of tumor invasion and severity, plasma IL-6 levels were continually elevated during tumor progression." (PMID 38505617, 2024). "In CD4+ T cells, IL6 favors differentiation of Th2 cells over Th1 and induces Th17 production, contributing to autoimmunity, chronic inflammation, and supporting tumor growth." (PMID 39766086, 2024). "IL-6 has been thought to play a key role in the cross-talk between different cell lineages within the tumor microenvironment." (PMID 38422751, 2024).
tumor (continued). "Studies have shown that AAs have higher levels of IL-6 and regulatory T-cells in circulation and within the tumor microenvironment when compared to other ethnic groups, which is an indicator of an immunosuppressive tumor environment." (PMID 38339362, 2024). "The upregulation of these molecules facilitates the recruitment of anti-tumor T-cells and triggers an immune response accompanied by the release of pro-inflammatory molecules like IL-1, IL-2, IL-6, IL-8, IL-12, VEGF, EGFR, IFN-α, IFN-ß and TNF-α." (PMID 39518094, 2024). "Within the tumor microenvironment, IL-6 facilitates the infiltration of inflammation-induced CD8+ T cells and cell-based models of NED and CRPC have been induced by IL-6 treatment in which PHF8 was found to be downregulated during NED and upregulated in CRPC." (PMID 39311138, 2024). "For example, MDSCs expressing the ER stress sensor CHOP inhibited T-cell function and promoted tumour growth by upregulating IL-6 expression." (PMID 38297380, 2024). "This binding causes lymphocytes to release cytokines IL-2, IL-1b, IL-6, TNF and Ifny into the medium, which leads to the appearance of cytotoxic lymphocytes in PBMC capable of lysing HLA-negative tumor cells." (PMID 38203798, 2024). "In the tumor microenvironment, IL-6 is overexpressed in PDAC tumors compared to adjacent normal tissue." (PMID 38689325, 2024). "Among all cytokines, only IL-6 mRNA expression was significantly downregulated in tumor cells co-cultured with AQP3-inhibited M2 macrophages." (PMID 39060229, 2024). "Since fibroblasts are the primary producers of IL-6, an increase in IL-6 levels is one of the key indicators of a change in fibroblast activity, which has a significant impact on tumor growth and therapeutic resistance." (PMID 38361760, 2024). "Similar to LPS signaling, the activation of the IL-1β pathway signals tumor cells to express immune mediators like IL-6, TNFα, CCL2, VEGF, PDGF-b, and MCSF." (PMID 38279220, 2024). "Consistent with our previous report, we observed significantly increased mRNA levels of TNF-α and IL-6 in the tumor tissues of AOM/DSS-treated VDUP1 KO mice compared to those in the tissues of WT mice." (PMID 39272794, 2024). "Various reports have shown that IL‐6 is involved in the proliferation, survival, invasion, and metastasis of tumor cells." (PMID 37452653, 2024). "IL6 produced by cancer-associated fibroblasts (CAF) augmented the production of proinflammatory cytokines such as IFNγ and IL17A by tumor-infiltrating T cells." (PMID 38819641, 2024). "Relatedly, IL-6 contributes to tumor-promoting inflammation in the tumor microenvironment by recruiting and activating MDSC’s, macrophages and tolerogenic dendritic cells." (PMID 38689325, 2024). "In conclusion, IL-6 secreted by senescent tumor cells facilitates macrophage CD73 expression via the JAK/STAT3 signaling pathway." (PMID 38323313, 2024). "For example, co-culture of tumor cell lines with autologous monocytes resulted in a significant elevation of IL-6 level in two out of the three tested CAR-T therapeutics compared to tumor cell culture alone." (PMID 39594640, 2024). "A positive correlation between plasma levels of IL-6 and tumor size was observed in patients with cardiac myxoma." (PMID 38396907, 2024). "Tumor-derived factors (i.e., IL-6, IL-10, IL-1β, PGE2, VEGF, GM-CSF, M-CSF, and IFN-γ) are implicated in the induction of MDSCs." (PMID 39272914, 2024). "Preclinical research has demonstrated that blocking IL-6 can inhibit tumor growth by enhancing the activity of CD4+/CD8+ effector T cells while suppressing Th17 and macrophages." (PMID 38304429, 2024). "In a recent study across multiple primary tumor types, we not only found elevated levels of IL-6 in the peritoneal fluid of patients with PC, but that the soluble receptor sIL6-Rα was present at exorbitant concentration regardless of disease state." (PMID 38689325, 2024).